SULT1C3 (sulfotransferase family 1C member 3)
Description:
[Isoform 1]: Sulfotransferase that utilizes 3'-phospho-5'-adenylyl sulfate (PAPS) as sulfonate donor. Has sulfotransferase activity towards various substrates, such as bile acids, thyroid hormones and toward xenobiotic compounds such as chloro phenols and hydroxypyrenes. Lithocholic acid appears to be the best substrate among the endogenous compounds tested and 3,3',5,5'-tetrachloro-4,4'-biphenyldiol shows the highest specific activity among the xenobiotic compounds. [Isoform 2]: Exhibits weak sulphating activity and only toward chloro phenols (pentachlorophenol and 3,3',5,5'-tetrachloro-4,4'-biphenyldiol).
Synonyms: ST1C3
Tractability: Small molecule: a structure with a bound ligand is known; it has a high-quality binding pocket. PROTAC: ubiquitination databases record sites on it.
Gene: Protein-coding gene on chromosome 2 (108,239,968 to 108,266,254, forward strand). Ensembl gene ENSG00000196228.
Subcellular location: Cytoplasm
Subcellular location (Human Protein Atlas): Cytosol
Gene Ontology:
Molecular function: 3'-phosphoadenosine 5'-phosphosulfate binding; alcohol sulfotransferase activity; aryl sulfotransferase activity; protein binding; sulfotransferase activity
Biological process: 3'-phosphoadenosine 5'-phosphosulfate metabolic process; xenobiotic metabolic process; sulfation; sulfur compound metabolic process
Cellular component: cytoplasm
Genetic constraint (gnomAD): Loss-of-function variants: 22 observed, 20.73 expected, observed/expected ratio (o/e) 1.06, 90% interval 0.76 to 1.51. The upper end of that interval is the gene's LOEUF score, 1.51, which puts it in group 6 of 6, group 1 being the genes least tolerant of losing a copy. Missense variants: 214 observed, 202.93 expected, observed/expected ratio (o/e) 1.05, 90% interval 0.94 to 1.18. Synonymous variants: 69 observed, 67.08 expected, observed/expected ratio (o/e) 1.03, 90% interval 0.85 to 1.26.
Homologues: Orthologues: macaque SULT1C3 (82% identical), pig SULT1C3 (59% identical), mouse Sult1c1 (58% identical), rabbit SULT1C3 (58% identical), rat Sult1c3 (58% identical), dog SULT1C3 (57% identical), zebrafish sult2st3 (36% identical), Drosophila melanogaster St3 (27% identical), Drosophila melanogaster St1 (27% identical), Drosophila melanogaster St4 (26% identical). Paralogues in human: SULT1C4 (55% identical), SULT1C2 (52% identical), SULT1B1 (49% identical), SULT1A3 (48% identical), SULT1A4 (48% identical), SULT1A2 (48% identical), SULT1A1 (47% identical), SULT1E1 (47% identical), SULT2A1 (33% identical), SULT2B1 (32% identical), SULT4A1 (28% identical), SULT6B1 (27% identical).